SNORD113-8 (small nucleolar RNA, C/D box 113-8)
Synonyms: 14q(I-8)
Gene: Small nucleolar RNA gene on chromosome 14 (100,943,451 to 100,943,524, forward strand). Ensembl gene ENSG00000200367.
Gene Ontology:
Biological process: RNA processing
Cellular component: nucleolus
Homologues: Orthologues: chimpanzee SNORD113-8 (100% identical), macaque SNORD113-8 (100% identical), guinea pig SNORD113-8 (96% identical), pig SNORD113-8 (96% identical). Paralogues in human: SNORD113-3 (82% identical), SNORD113-6 (82% identical), SNORD113-4 (80% identical), SNORD113-7 (80% identical), SNORD113-5 (78% identical), SNORD113-9 (77% identical), SNORD114-12 (70% identical), SNORD113-2 (69% identical), SNORD114-26 (68% identical), SNORD114-3 (68% identical), SNORD114-10 (66% identical), SNORD114-14 (66% identical), and 26 more.